MIR493HG (MIR493 cluster host gene)
Gene: Long non-coding RNA gene on chromosome 14 (100,836,269 to 100,947,194, forward strand). Ensembl gene ENSG00000258399.
Gene Ontology:
Cellular component: nucleus